SLC9B2 (solute carrier family 9 member B2)
Description:
Electroneutral Na(+) Li(+)/H(+) antiporter that extrudes Na(+) or Li(+) in exchange for external protons across the membrane. Uses the proton gradient/membrane potential to extrude sodium. Contributes to the regulation of intracellular pH and sodium homeostasis (By similarity). Also able to mediate Na(+)/Li(+) antiporter activity in kidney. May play a physiological role in renal tubular function and blood pressure homeostasis (By similarity). Plays an important role for insulin secretion and clathrin-mediated endocytosis in beta-cells (By similarity). Involved in sperm motility and fertility (By similarity). It is controversial whether SLC9B2 plays a role in osteoclast differentiation or not (By similarity).
Synonyms: NHA2; NHEDC2; FLJ23984; NHE10
Tractability: Small molecule: a structure with a bound ligand is known. Antibody: UniProt places it where antibodies can reach, with high confidence; its Gene Ontology location is reachable by antibodies, with high confidence; UniProt predicts a signal peptide or a membrane-spanning region. PROTAC: ubiquitination databases record sites on it; its protein half-life has been measured.
Target class: SLC superfamily of solute carriers; SLC09 family of sodium/hydrogen exchangers; Electrochemical transporter; Transporter
Gene: Protein-coding gene on chromosome 4 (103,019,868 to 103,085,829, reverse strand). Ensembl gene ENSG00000164038.
Subcellular location: Cell membrane; Mitochondrion membrane; Endosome membrane; Recycling endosome membrane; Cytoplasmic vesicle, secretory vesicle, synaptic vesicle membrane; Cell projection, cilium, flagellum membrane; Basolateral cell membrane; Apical cell membrane
Subcellular location (Human Protein Atlas): Nucleoplasm; Cell Junctions
Pathways (Reactome):
Transport of small molecules: Stimuli-sensing channels
Gene Ontology:
Molecular function: identical protein binding; lithium:proton antiporter activity; protein binding; sodium:proton antiporter activity; antiporter activity
Biological process: lithium ion transport; sodium ion transport; flagellated sperm motility; monoatomic ion transmembrane transport; sodium ion homeostasis; transmembrane transport; clathrin-dependent endocytosis; monoatomic cation transport; proton transmembrane transport; regulation of insulin secretion involved in cellular response to glucose stimulus; sodium ion transmembrane transport
Cellular component: mitochondrial membrane; mitochondrion; plasma membrane; apical plasma membrane; basolateral plasma membrane; endosome membrane; mitochondrial inner membrane; recycling endosome; recycling endosome membrane; sperm principal piece; intracellular vesicle; membrane; synaptic vesicle membrane
Genetic constraint (gnomAD): Loss-of-function variants: 34 observed, 45.62 expected, observed/expected ratio (o/e) 0.75, 90% interval 0.57 to 0.99. The upper end of that interval is the gene's LOEUF score, 0.99, which puts it in group 4 of 6, group 1 being the genes least tolerant of losing a copy. Missense variants: 587 observed, 619.96 expected, observed/expected ratio (o/e) 0.95, 90% interval 0.88 to 1.01. Synonymous variants: 198 observed, 221.62 expected, observed/expected ratio (o/e) 0.89, 90% interval 0.8 to 1.
Homologues: Orthologues: chimpanzee SLC9B2 (99% identical), macaque SLC9B2 (99% identical), dog SLC9B2 (87% identical), rabbit SLC9B2 (85% identical), pig SLC9B2 (85% identical), rat Slc9b2 (82% identical), mouse Slc9b2 (81% identical), guinea pig SLC9B2 (79% identical), tropical clawed frog slc9b2 (65% identical), zebrafish SLC9B2 (58% identical), Drosophila melanogaster Nha1 (34% identical), Drosophila melanogaster Nha2 (30% identical), and 3 more. Paralogues in human: SLC9B1 (53% identical).
Diseases named in the same sentence as SLC9B2 in open-access papers:
SLC9B2 is named in the same sentence as 23 diseases in open-access papers, as found by Europe PMC text mining. Sharing a sentence is not in itself a finding about the gene and the disease. The quoted sentences say what the papers report.
diabetes (4 papers, 2019 to 2025). "Based on its tissue expression pattern, genomic location, and phloretin sensitivity, NHA2/SLC9B2 activity has been linked to the Na+(Li+) counter-transport activity associated with the development of essential hypertension and diabetes in humans." (PMID 40362458, 2025). "What’s more, SLC9B2 is related to the pathogenesis of diabetes and hypertension, and is crucial for sperm motility and fertility." (PMID 41019085, 2025). "The Na+/H+ exchanger SLC9B2, also known as NHA2, correlates with the long-sought-after Na+/Li+ exchanger linked to the pathogenesis of diabetes mellitus and essential hypertension in humans." (PMID 35173351, 2022). "CDKAL1, RREB1, and PPARG were not significant in either arm of the diabetes stratified analysis, while RAI1 and SLC9B2 were significant in the non-diabetes group." (PMID 31451708, 2019).
autosomal dominant polycystic kidney disease (2 papers, 2024 to 2025). Autosomal dominant form of polycystic kidney disease. "A previous study suggested the increased expression of SLC9B2 had a positive relationship with Autosomal-dominant polycystic kidney disease." (PMID 38596213, 2024).
cyst (2 papers, 2022 to 2025). A sac-like closed membranous structure that may be empty or contain fluid or amorphous material. "In polycystic kidney disease, SLC9B2 is significantly upregulated and positively correlated with cyst size, regulated by the polycystin-1/Ca2+/NFAT signaling axis, which can be induced by vasopressin and methylxanthine drugs." (PMID 41019085, 2025).
male infertility (2 papers, 2019 to 2022). The inability of the male to effect fertilization of an ovum after a specified period of unprotected intercourse. "The importance of NHA1 and NHA2 (SLC9B2) was demonstrated by genetically modified animals; single knock-out (NHA1 KO) mice show a slight reduction in male fertility, and double knock-out (NHA1/2 dKO) mice show complete male infertility." (PMID 31372239, 2019).
Crohn disease (1 paper, 2024). A gastrointestinal disorder characterized by chronic inflammation involving all layers of the intestinal wall, noncaseating granulomas affecting the intestinal wall and regional lymph nodes, and transmural fibrosis. "The expression level of SLC9B2 was identified significantly upregulated in Crohn’s disease." (PMID 38596213, 2024).
osteosarcoma (1 paper, 2023). A usually aggressive malignant bone-forming mesenchymal neoplasm, predominantly affecting adolescents and young adults. "Several amino acid transporters, such as SLC44A5, SLC9B2, and SLC37A2, were significantly decreased after NACT, which might contribute to the amino acid deprivation in osteosarcoma after NACT." (PMID 37457661, 2023).
infection (1 paper, 2025). The state of being infected such as from the introduction of a foreign agent such as serum, vaccine, antigenic substance or organism. "Additionally, the secretion of sodium ions into the intestinal lumen mediated by SLC9B2 may contribute to a more hypertonic environment, potentially affecting Leishmania during infection or influencing the local microbiota." (PMID 40572192, 2025).
SLC9B2 also shares sentences with these, for which no sentence is quoted: essential hypertension (4 papers); Hypertension (4); Infertility (3); polycystic kidney disease (2); autism (1); breast carcinoma (1); Christianson syndrome (1); fertility disorders (1); Gitelman syndrome (1); Glucose intolerance (1); Hepatic steatosis (1); Hypoglycemia (1); Insulin resistance (1); kidney disease (1); neurological diseases (1); Obesity (1).